INS (insulin)
Diseases named in the same sentence as INS in open-access papers (continued):
Sharing a sentence is not in itself a finding about the gene and the disease.
diabetes (continued). "Secondly, as our patients with diabetes were not newly diagnosed and were treated with anti-diabetic drugs and/or insulin, we cannot perform the association between the SNPs in FNDC5 and clinical parameters in patients." (PMID 25369206, 2014). "One form of cutaneous amyloidosis is related to local subcutaneous injections of insulin, the incidence rate of which may be underestimated when considering the high prevalence of diabetes mellitus and insulin treatment." (PMID 25009591, 2014). "Of the 748 eligible respondents, one third were using insulin to manage their diabetes." (PMID 24902877, 2014). "T2D is the most common form of diabetes and individuals are characterized by disorders of insulin action and secretion, either of which may be the predominant feature." (PMID 25162051, 2014). "The subcutaneous delivery of insulin in diabetes firstly exposes this hormone to more evenly distributed IR-A:IR-B in peripheral (for example muscle and adipose) tissue, delaying the liver response and hence increasing the risks of misbalanced glycaemic states." (PMID 25286859, 2014). "Therefore the aim of this study is to assess knowledge of insulin use among insulin requiring patients with diabetes, with the goal of identifying gray areas for future educational interventions." (PMID 24397956, 2014). "Diabetes mellitus (DM) is a complex metabolic disorder that has multiple etiologies and is characterized by chronic hyperglycemia as a result of defects in insulin secretion, insulin action, or both." (PMID 25945127, 2014). "We also show that women with glucose intolerance or diabetes postpartum have an impaired beta-cell function and lower insulin sensitivity, remaining significant after adjustment for age, BMI, ethnicity, breastfeeding, contraception, multiparity, and corticoid treatment." (PMID 25180037, 2014). "Behavioral and psychosocial aspects of diabetes care in adolescents with type 1 diabetes are particularly concerning because mental health issues can interfere with diabetes self-management (e.g., self-monitoring of blood glucose levels and injecting insulin as recommended)." (PMID 24637957, 2014). "In a recent USA case-control study, diabetic patients treated with insulin had an insignificant 2.2-fold higher risk of bladder cancer while compared to subjects without diabetes." (PMID 24466131, 2014). "Diabetes mellitus refers to a metabolic disorder of multiple etiology characterized by chronic hyperglycaemia with disturbances of carbohydrate, fat, and protein metabolism resulting from disturbed insulin secretion, insulin action, or both." (PMID 24818152, 2014). "Professional diabetes organizations recommend that basal or premixed insulin could be used as the initial insulin therapy." (PMID 24620742, 2014). "In people with type 2 diabetes (the commonest form of diabetes), blood sugar control fails because the fat and muscle cells that normally respond to insulin by removing excess sugar from the blood become less responsive to insulin." (PMID 24453948, 2014). "Diabetes mellitus is a metabolic disease with deficiency of secretion or action of endogenous insulin, features of hyperglycemia, and no definite cause." (PMID 25114914, 2014). "The diabetes-induced superoxide level decrease was significantly reversed by insulin treatment." (PMID 25223305, 2014). "The group of patients treated with insulin detemir, however, had a significantly shorter duration of diabetes (8.1 vs. 8.6 years, p = 0.03), and a higher baseline HbA1c (9.7 vs. 9.2%, [83 vs. 77 mmol/mol] p = 0.003) compared with patients treated with insulin glargine." (PMID 25048824, 2014). "Our results show that animals with untreated hyperglycemia in type 1 diabetes mellitus (T1DM) respond to acute insulin challenge much better than the diabetic animals treated with insulin, suggesting that hyperglycemia itself does not cause insulin resistance but treatment of T1DM with insulin does." (PMID 24741073, 2014).
diabetes (continued). "Diabetes mellitus is a syndrome of impaired carbohydrate metabolism, lipids and proteins caused by lack of insulin secretion or the tissues decreased sensitivity to insulin metabolic effects." (PMID 25560330, 2014). "The variables that were strongly concurrent between the 1st and 4th quartiles for both formulas comprise BMI, waist/height ratio, subscapular skinfold, total dose insulin IU/lean mass(kg), age, diabetes duration and thoracoabdominal fat (absolute and percentage)." (PMID 25937839, 2014). "It remains to be fully elucidated whether conventional hypoglycaemic agents (metformin, sulfonylureas, thiazolidinediones [TZDs] or insulin) affect lung cancer incidence in patients with diabetes." (PMID 24924771, 2014). "Liver as the major target organs of insulin plays important roles in the development of insulin resistance and type 2 diabetes mellitus, and the underlying mechanisms are still not fully understood." (PMID 24918756, 2014). "In conditions associated with lack of insulin such as diabetes, hippocampal Na+/K+-ATPase activity was reduced, indicating that insulin is essential for maintaining the normal function of this pump." (PMID 25161691, 2014). "resistance to insulin as well as increase in generation of reactive oxygen species (ROS) and oxidative stress which result in destruction of insulin producing β-cells in pancreatic tissue, have critical roles in mechanism of induction of diabetes." (PMID 24495344, 2014). "Therefore, understanding beta-cell generation and insulin production/secretion holds keys to understand and potentially cure diabetes." (PMID 25628604, 2014). "Finally, changes in glucose sensitivity under pathological conditions (e.g., recurrent insulin-hypoglycemia, diabetes) will be addressed." (PMID 25540613, 2014). "Animal studies further support the hypothesis that epigenetic modifications in pancreatic islets may lead to altered gene expression, impaired insulin secretion and subsequently diabetes." (PMID 24603685, 2014). "Dermatologists should be aware that patients with psoriasis both on anti-TNF therapies and insulin for diabetes may experience hypoglycemia." (PMID 25713604, 2014). "Type 2 diabetes mellitus (T2DM) is a chronic metabolic disease characterized by dysregulation of glucose and lipid metabolism, which mainly linked to abnormal blood insulin levels or insensitivity of target organs to insulin." (PMID 25431772, 2014). "It is hoped that in this way—by experimenting with different basal and bolus regimens—users might be able to learn a bit more about balancing insulin and diet in diabetes, even with an insulin pump." (PMID 24511312, 2014). "In addition to metformin, two antidiabetic agents, insulin and rosiglitazone, had been investigated for their effect on the link between diabetes and AD." (PMID 24782665, 2014). "Diabetes is a group of metabolic diseases caused by reduced or absent insulin secretion and it makes cells less sensitive to insulin." (PMID 25177729, 2014). "When quantitative variables in the multivariate model were kept constant, quality of life had an association with the duration of diabetes that depended on the presence or absence of DR or insulin therapy." (PMID 25138117, 2014). "We then tested whether inflammation was also increased in skeletal muscles of a nutritional model of diabetes and if the insulin sensitizing agent rosiglitazone could improve this inflammatory state." (PMID 25337938, 2014). "Vitamin D might help controlling diabetes mellitus through increasing insulin secretions and increasing sensitivity to this hormone." (PMID 25340161, 2014). "In contrast, some intervention trials demonstrated a greater improvement in insulin sensitivity, glycemic control and a reduction in oxidative stress markers in T2D patients consuming a vegetarian diet compared with those consuming a traditional diabetes diet." (PMID 25222490, 2014).
diabetes (continued). "For example, male transgenic mice overexpressing human H-Ras develop β-cell degeneration and onset of diabetes, exhibiting hyperglycemia, glycosuria, and hypoinsulinemia, and Ras inhibition in mouse cells leads to increased insulin sensitivity and glucose uptake." (PMID 25421944, 2014). "Hence, present compelling evidence to suggest that, despite high BMI, subjects with diabetes and islet autoantibodies exhibit severe beta cell dysfunction at baseline and in response to a potent insulin secretagogue (arginine)." (PMID 25226365, 2014). "Although α7nAChR agonists have not yet been investigated for eating behavior effects in humans, preliminary animal work supports this idea, finding peripheral effects such as improved insulin sensitivity and reduced weight gain and metabolic changes in a model of diabetes." (PMID 24936193, 2014). "Although this result represents low levels compared with the necessary concentration of human insulin to protect the mouse from diabetes, an early detection is significant compared with the fact that the development of maximal insulin secretion requires at least 3 months post-implant." (PMID 24963634, 2014). "Additionally, weight gain, hypoglycemia, edema, gastrointestinal disturbances, and insulin resistance are observed in diabetes patients who receive long-term insulin treatment." (PMID 24738047, 2014). "Interestingly, intranasal aerosol application of the whole insulin molecule in NOD mice led to induction of CD8+γδ T cells capable of preventing development of diabetes in an adoptive cotransfer model." (PMID 24728138, 2014). "In Tawney 44% of the study population had diabetes and 29% were treated with insulin." (PMID 25423489, 2014). "Therefore, finding strategies to improve peripheral insulin sensitivity is important as a means to control diabetes, hyperlipidemia and complications." (PMID 25375187, 2014). "Based on these observations, these authors concluded that subjects at risk for T2D exhibit intrinsic differences in palmitate‐mediated regulation of glycogen synthase and PP2A, thereby contributing to the alterations in insulin regulation of glucose metabolism in diabetes." (PMID 25347859, 2014). "These concerns and beliefs were the results of having good knowledge about the diabetes and insulin, experiential learning, as well as doctors’ practical and emotional support that helped them to accept insulin therapy and become efficient in self-care management." (PMID 24164794, 2013). "Therefore, the downregulation of PDX-1 importantly affects insulin production favoring beta-cell secretory dysfunction and potentially diabetes." (PMID 23737653, 2013). "The premise that not every subject with type 2 diabetes benefits from intensive glycemic control, consequently leads setting up flexible regimens of treatment with diabetes drugs (including insulin) and providing individualized glycemic goals and ongoing professional support." (PMID 23721170, 2013). "Our finding that SMBG can trigger both positive and negative emotional responses, depending on the reading, corresponds with the literature that suggests that there is a relationship between distress and SMBG practice among non-insulin treated individuals with diabetes." (PMID 24119213, 2013). "Thus, in animal models, exposure to TCDD mimics the feature of reduced insulin secretion observed in the clinical progression of prediabetes to overt diabetes." (PMID 23651634, 2013). "In obese T2D subjects, a prompt diabetes remission is observed after bariatric surgery and insulin sensitivity is restored along with the normalization of the first phase of insulin secretion." (PMID 23437106, 2013). "Our study extended the previous results and demonstrated for the first time that diabetes inhibited sevoflurane post-conditioning induced neuroprotection and this protective strategy could be restored by insulin treatment." (PMID 23991188, 2013).
diabetes (continued). "Individuals with abnormal insulin sensitivity are also at increased risk of arterial stiffness, even in the absence of diabetes and hypertension." (PMID 23671853, 2013). "Currently, the therapy for diabetes aims at maintaining or improving the secretory capacity of the pancreatic β-cell and increasing sensitivity of the target organs such as liver, muscle and adipose tissues, to insulin." (PMID 24499158, 2013). "I was afraid that insulin might ruin my health” (3 years of insulin use/ 5 years of having diabetes)." (PMID 24164794, 2013). "Considerable effort is being invested in the development of protocols for directed differentiation of embryonic stem cells to insulin-producing beta cells that could be transplanted to cure diabetes." (PMID 23940571, 2013). "Exendin-4 is a long-acting glucagon-like peptide-1 receptor agonist approved for the treatment of type 2 diabetes mellitus that not only effectively induces glucose-dependent insulin secretion to regulate blood glucose levels but also reduces apoptotic cell death of pancreatic β-cells." (PMID 24312624, 2013). "Thus, our results provide important observations for further understanding the effects of defective insulin signalling and diabetes on male reproductive function." (PMID 23741292, 2013). "A low plasma adiponectin level may be valid predictive factor of diabetes development in the future and may be related with reduction of hepatocytes insulin sensitivity, and this phenomenon may co-trigger development of hyperglycemia." (PMID 22829443, 2013). "Indeed, the diabetes impacts on the testicular tissue due to insufficient production of insulin which in turn results in reducing the sertoli and leydig cells endocrine function." (PMID 24639728, 2013). "The average duration of diabetes was 4.5 years (SD: 5.9) with 12 (40%) treated with insulin." (PMID 23936778, 2013). "Present population epidemiological and animal studies suggest that CGA, which in vivo can regulate glucose and lipid metabolism and improves insulin sensitivity, may be capable of preventing and treating obesity, diabetes mellitus, and metabolic syndrome." (PMID 24062792, 2013). "LV fat content in these diabetic rats was significantly lower than that in the non-diabetic controls, consistent with the severely insulin-deficient model of diabetes employed in this study." (PMID 23368770, 2013). "After initiation of insulin, the participants’ active effort to seek for knowledge on diabetes and its treatment might contribute to their insulin acceptance." (PMID 24164794, 2013). "Historically, insulin has been the first available therapy for diabetes." (PMID 24348585, 2013). "Glycemic control decreased and insulin use increased with the duration of diabetes." (PMID 23800082, 2013). "Indeed, the failure of the agonistic stimulation of the insulin axis deeply impacts on the biology of diabetics' cells." (PMID 23484099, 2013). "Numerous studies have now shown that while insulin’s vascular effects may be blocked in diabetes, exercise still maintains its ability to increase the distribution of blood flow through muscle." (PMID 24772374, 2013). "A case study of diabetes therapy with real patents' data was used in the evaluation experiment which simulates a therapeutic decision-support scenario where real-time blood glucose level is predicted based on various insulin intakes and life-time events." (PMID 24163813, 2013). "The NSY mouse closely imitates human T2DM in which the characteristics of NSY mouse are mild obesity with abdominal and visceral fat accumulation, accompanied by impaired insulin secretion and moderate insulin resistance contributing to diabetes development in an age-dependent manner." (PMID 23671868, 2013).
diabetes (continued). "As compared to the reference group, men and women with diabetes and prediabetes, respectively, presented significantly higher levels of glucose and insulin, and also higher values of BMI, SAD, blood pressure, LDL cholesterol and triglycerides; HDL values were significantly lower." (PMID 23630613, 2013). "Overall, 27% of the diabetes cohort was treated with insulin." (PMID 24260140, 2013). "We also examined whether hyperglycemic correction with insulin would restore anesthetic post-conditioning in diabetes." (PMID 23991188, 2013). "Long-term increases in leptin or insulin lead to receptor desensitization and insulin or leptin “resistance” increasing plasma glucose levels and fat accumulation, producing eventually obesity and diabetes." (PMID 23781199, 2013). "Insulin has neuroprotective effects and the lack of insulin, as a neuro-trophic factor, encourages the loss of retinal neurons observed in diabetes and possibly in hyperglycemic premature babies with ROP." (PMID 24278148, 2013). "This suggests that refined diabetes classification may require both immune and metabolic testing, with the IS Score being a useful addition to identify insulin resistant phenotypes." (PMID 24023937, 2013). "However, self-reported diabetes medication (Insulin: 10%; OHAs: 58%) was similar to that observed in the PBS data (71%)." (PMID 24245780, 2013). "This phenomenon is often termed “psychological insulin resistance” and may encompass a range of negative attitudes towards insulin, including weight concerns, needle phobia and the belief that insulin initiation signifies failure to self-manage diabetes." (PMID 24223860, 2013). "“I don’t think using needle is practical” (3 years of insulin use/ 6 years of having diabetes)." (PMID 24164794, 2013). "High fructose consumption may lead to oxidative stress and metabolic alterations, whereas chronic consumption reduces insulin sensitivity and glucose tolerance, thus speeding up diabetes onset." (PMID 23698776, 2013). "However, it is difficult to explain the most obvious increase in cancer mortality among women with insulin-treated diabetes found in this study." (PMID 23837500, 2013). "The predicted increase in ghrelin production, coupled with the marked reduction in insulin expression, may explain the rapid onset of diabetes in our animals." (PMID 23326594, 2013). "This new generation PPARγ sparing insulin sensitizer may provide an initial tool for relieving inherent human islet insulin signaling pathway resistance that is necessary to preserve the β-cell phenotype during β-cell expansion for the treatment of diabetes." (PMID 23650507, 2013). "Indeed, adiponectin promotes insulin sensitivity, and thus, is decreased in patients with obesity, diabetes, or metabolic syndrome." (PMID 24379815, 2013). "In both genders, the participants who developed incident MetS were older, had higher SBP and DBP, TG, FPG, basal insulin, BMI, WC and positive family history of diabetes but lower eGFR and HDL-C compared with participants free of MetS at the end of follow-up (P<0.05 for all measures)." (PMID 24086723, 2013). "Given the financial and emotional implications of practicing SMBG, it is important for healthcare providers to consider patients’ clinical, financial and social context, prior to advising the use and frequency of SMBG among non-insulin treated individuals with diabetes." (PMID 24119213, 2013). "Additionally, there are reports of reduced β-islet cell mass, decreased insulin secretion and altered glucose metabolism in HD mouse models and an increasing prevalence of diabetes mellitus in HD patients." (PMID 23967334, 2013). "Diabetes mellitus is defined as hyperglycemia that is associated with inadequate insulin secretion, either in the presence or absence of impaired insulin action." (PMID 23576986, 2013).